IGF1R (insulin like growth factor 1 receptor)
Diseases named in the same sentence as IGF1R in open-access papers (continued):
Sharing a sentence is not in itself a finding about the gene and the disease.
tumor (continued). "In the present study, we utilized the METABRIC patient database and single-cell RNA sequencing of two IGF1R loss-of-function mouse tumor models to uncover how IGF1R signaling regulates intrinsic epithelial cell signaling to suppress metastasis." (PMID 36568144, 2022). "Following induction of lung metastasis, IGF1R-deficient lungs also demonstrated a reduced tumor burden, and decreased expression of tumor progression markers, p-IGF1R and p-ERK1/2." (PMID 35688943, 2022). "A study developed IGF1 receptor-directed multifunctional theragnostic NPs for the targeted delivery of Dos into IGF1R-expressing drug-resistant tumour cells and tumour-associated stromal cells." (PMID 36014691, 2022). "ERα functions as a transcription factor for genes associated with tumor cell proliferation and growth, such as insulin-like growth factor-1 receptor (IGF1R), cyclin D1, anti-apoptotic BCL-2 protein, and vascular endothelial growth factor (VEGF)." (PMID 36060947, 2022). "Two studies highlighted the role of dendritic cells and tumor-associated myeloid cells in supporting T-ALL growth in stromal niches via IGF-1R activation, emphasizing the relevance of this signaling pathway in the pathobiology of T-ALL." (PMID 35217681, 2022). "To test how loss of IGF1R alters the primary tumor phenotype, we made use of two distinct mouse models." (PMID 36568144, 2022). "LLC cell tumorigenic capacity was evaluated by measuring the heterotopic tumor volume, which was lower in IGF1R deficient (CreERT2) vs. Igf1rfl/fl mice." (PMID 35688943, 2022). "Here we show loss of IGF1R in the primary tumor promotes metastasis by modulating cadherin expression and altering epithelial cell properties to decrease cellular adhesion." (PMID 36568144, 2022). "In 96 tumours investigated by high‐coverage exome sequencing, we detected missense mutations in: IGF1R (n = 1), IGF2R (n = 1) and IGFBP5 (n = 2)." (PMID 33295144, 2021). "The overexpression of ACLY and IGF1R was correlated with a higher risk of lymph node and distant metastasis, worse tumor differentiation, and higher AJCC stage." (PMID 34075028, 2021). "IGF2 signals through IGF1R, which is one of the crucial receptor tyrosine kinases implicated in tumor development." (PMID 33407516, 2021). "Inaddition, it was reported that the up-regulation of IR canenhance multistage tumor progression and cause intrinsicresistance to insulin-like growth factor-1 receptor (IGF-1R) targeted therapy." (PMID 34308576, 2021). "In approximately 5% of thyroid cancers, overexpression of insulin-like growth factor 2 binds to protein 3 (IGF2BP3) and low expression of IGF1R inhibit the abnormal growth of tumour cells caused by IGF2BP3." (PMID 34923978, 2021). "m-IGF1R expression in high grade PanIN lesions correlated with m-IGF1R expression of the surrounding tumor tissue (p = 0.031; loss of significance upon multiple testing)." (PMID 34638472, 2021). "More importantly, IGF-1 and IGF-1R expression were correlated with tumor mutation burden (TMB), microsatellite instability (MSI), mismatch repair (MMR), and DNA methyltransferase (DNMT) of different types of cancers." (PMID 34804946, 2021). "There was an inverse association between miR-143 and IGF-1R mRNA expression levels which showed that the miR-143 exerts its tumor-suppressive role through IGF-1R regulation." (PMID 33183321, 2020). "Our survival data appear to be consistent with our associations between IGF1R expression and clinicopathological parameters: IGF1R expression was associated with more differentiated tumors, less lymphatic vessel invasion and a lower tumor size at diagnosis." (PMID 32727431, 2020).
tumor (continued). "As CreER‐LoxP system‐mediated gene knockout cannot be 100% efficient, we suspected that the tumors developed in the CKO_NG2‐CreER_IGF1R (flox/flox) model were due to the incomplete knockout of IGF1R allele in these tumor cells." (PMID 33173731, 2020). "There was a non-significant trend to increased IDH1 mutation in moderate/strong IGF-1R tumours (p = 0.12)." (PMID 31857716, 2020). "While less profound, a similar phenotype was observed when one IGF1R allele was removed, suggesting IGF1R has dosage effects on tumor initiation and /or progression." (PMID 33173731, 2020). "Insulin-like growth factor 1 receptor (IGF1R) was associated with intrinsic resistance to idelalisib in tumor cells." (PMID 32197371, 2020). "Intriguingly, tumor IGF1R expression is associated with lymphatic invasion and predicts shorter progression-free survival in EGFR-mutant but not EGFR–wild type NSCLC, suggesting a unique interplay between EGFR and IGF1R pathways in this type of malignancy." (PMID 32292420, 2020). "IGF1R is a transmembrane tyrosine kinase receptor and considered as a potential therapeutic target due to associations of IGF1R overexpression with tumor metastasis, drug resistance, and poor prognosis in multiple cancer types." (PMID 32570949, 2020). "IGF1R was associated with tumor localization, local tumor growth, lymphatic vessel invasion, grading, mismatch repair protein expression status and IR-expression." (PMID 32727431, 2020). "In LSCC, a hypoxic tumor microenvironment exposed to xenobiotic toxicity nicotine can potentially cause the dysregulation of IGF-1R, ITGB1 and TNS1 signaling pathways." (PMID 31217907, 2019). "Insulin-like growth factor-1 receptor (IGF-IR) activation is associated with the invasion and metastases in BCa and it has a role with the estrogen receptor in promoting tumor growth." (PMID 31456748, 2019). "As a predictive marker, IGF-1R has been demonstrated to be associated with tumor grade and poor survival in a variety of solid tumors in many studies." (PMID 31467485, 2019). "This deficiency, which correlates with higher tumour grade and shorter overall survival, leads to the activation of type 1 insulin-like growth factor-1 receptor (IGF1R)." (PMID 30701095, 2019). "In terms of RCC specific signaling pathways deregulation it was previously reported that receptor for activated C kinase 1 (RACK1) is a direct mediator between loss of pVHL function and IGF1R signaling in RCC tumor cells." (PMID 30929166, 2019). "IGF-1R is highly expressed in many cancers, and this is linked to tumor development, invasion, and metastasis." (PMID 31555212, 2019). "ERα is a transcription factor for genes associated with cell survival, proliferation, and tumor growth (e.g., genes for insulin-like growth factor-1 receptor (IGF1R), cyclin D1, anti-apoptotic BCL-2 protein, vascular endothelial growth factor (VEGF))." (PMID 30382472, 2019). "In conclusion, coffee consumption was negatively associated with tumor-specific IGF1R levels only among normal-weight patients." (PMID 29928262, 2018). "PLCG1 is generally activated by growth factor receptors such as vascular endothelial growth factor receptors (VEGFRs), insulin-like growth factor 1 receptor (IGF-1R) and FGFRs and has been linked to metastatic tumour progression." (PMID 29188362, 2018). "In conclusion, a higher coffee consumption was associated with lower tumor-specific IGF1R expression, although only among normal-weight patients." (PMID 29928262, 2018). "In cervical cancer animal models, treatment with IGF1R antibodies inhibited tumor growth and caused tumor regression." (PMID 29922232, 2018). "Activation of downstream pathways of RTKs, such as ERBB2, EGFR, and IGF1R, has been proven to be related to tumor cell anoikis resistance, and IBC cells have been associated with more evasion of anoikis which is consistent with our findings." (PMID 30086764, 2018).
tumor (continued). "Whereas the opposite association is found in some other malignancies where IGF-1R exacerbated malignant transformation and tumor cell proliferation." (PMID 28137302, 2017). "Dysregulation of various components of the IGF-1R system has been reported at different tumor stages and has been implicated in tumorigenesis through non-canonical pathways." (PMID 28968951, 2017). "High IGF1R and SphK1 protein co-expression in tumor tissue was associated with improved OS specifically in ER-positive disease and stratified for anti-endocrine therapy." (PMID 29207959, 2017). "A meta-analysis suggested IGF1R positive expression as an unfavorable factor associated with smoking status and tumor size for disease free survival in NSCLC patients." (PMID 27463019, 2016). "The ability of triterpenes is evidence to inhibit the inflammation in the tumor micron-environment associated with greater reduction of Cox-2 and Twist1 proteins more inhibition of activation of IGF-1R, Stat3, and Src." (PMID 27378920, 2016). "Since changes in membranous IGF-1R expression were significantly associated with tumor stage, multivariate Cox regression analysis was performed." (PMID 25680198, 2015). "Upregulation of membranous IGF-1R was significantly associated with high tumor stage at diagnosis (χ2-test, p = 0.04)." (PMID 25680198, 2015). "Collectively, it was concluded that the tumor suppressor role of miR-99a is associated with IGF-1R pathway regulation." (PMID 25663868, 2015). "The efficacy of IGF-1R targeting in the clinics depends on major factors such as the role of IFGR in itself in the tumours, inhibition potential of siRNAs and antisense therapies in vivo, and compensation of other signalling pathways due to IGFR loss." (PMID 25866791, 2015). "Levels of mRNA and protein expression, copy number, and mutation status were compared with tumor response to anti-IGF1R antibody therapy in 4 OS xenograft models." (PMID 25170759, 2014). "The expression of N-cadherin was associated with clinical stage (p=0.0354), distant metastasis (p=0.0271) and survival (p=0.0014), while the expression of IGF1R was associated with tumor size (p=0.0101), distant metastasis (p=0.0259) and survival (p=0.0253)." (PMID 25096247, 2014). "In a large recent tumor tissue microarray protein expression study including primary tumors of some 800 PCa patients the expression level of IGF1R was associated with a worse prognosis as was a decreased expression of PTEN." (PMID 24809298, 2014). "Because of the finding of GRB10 mutation in case #2, mutational analysis of GRB10 was also performed on tumor from case #3 (who also achieved a CR after IGF1R inhibitor therapy) and, remarkably, was also positive by Sanger sequencing." (PMID 25119929, 2014). "IGF1R expression had a significant association with histological grade of tumor differentiation, and also tended to be associated with abundant stroma." (PMID 23962053, 2013). "The IGF1R gene was sequenced in 47 ES tumor samples and 8 ES cell lines; only one tumor sample showed a nonsynonymous mutation, R1353H, in a region with low functional impact." (PMID 23431249, 2013).
tumor (continued). "Collectively, these results suggest that loss of expression of IGFBPs in tumour cells treated with EGFR-TKIs results in the activation of IGF1R signalling, which in turn mediates resistance to EGFR antagonists." (PMID 24339922, 2013). "The data implicating IGF-1 and IGF-2 in cancer risk and tumor progression have positioned IGF1R as a prime oncolgy therapeutic target, anticipated to have activity against a number of human malignancies." (PMID 23383308, 2013). "Shorter PFS was associated with α-IGF1R (P=0.028), pBad overexpression (P=0.003), and tumour recurrence in the liver (P=0.003) or the bone (P=0.001)." (PMID 22454081, 2012). "Studies with monoclonal antibodies to IGF-1R have implicated this receptor as important in PCa progression in androgen-sensitive as well as -resistant tumor models." (PMID 23300537, 2012). "The IGF1R receptor has been implicated in the development of tumours in various settings and we therefore anticipated that inhibition of the IGF1R would be of potential therapeutic significance in this model." (PMID 21811251, 2011). "The type 1 insulin-like growth factor receptor (IGF1R) has been implicated in various aspects of tumour development and metastasis with overexpression of IGF1R and its ligands IGF1 and IGF2, a common finding in malignant disease." (PMID 21811251, 2011). "In a pancreatic tumour model, fibronectin interaction with α5β3 caused transactivation of the insulin-like growth factor-1 receptor and increased tumour cell survival." (PMID 19173736, 2009). "Blockade of IGF-1R has been convincingly shown to cause massive apoptosis of tumour cells in vivo, to inhibit tumorigenesis and block tumour invasion and metastasis." (PMID 15956962, 2005). "Disregulation of the IGF system through over-stimulation of the IGF1 receptor (IGF1R) has been implicated in tumour development and maintenance of the transformed phenotype." (PMID 15471544, 2004). "Mechanistically, miR-145 disrupts TGF-β signaling cascades that usually promote M2 polarization, angiogenesis, and metastatic progression, while simultaneously inhibiting IGF1R-mediated survival and proliferation signals that support tumor-associated macrophage accumulation." (PMID 41463227, 2025). "In tumor cells, IGF-1R activation can cause angiogenesis, invasion, and metastasis." (PMID 41303367, 2025). "Hence, various studies have demonstrated that IGF1R inhibition and downregulation cause substantial in vivo tumor cell death, impede tumorigenesis, and trigger a host response that eliminates surviving tumor cells." (PMID 38791406, 2024). "Interestingly, adhesion-dependent IGF1R Tyr1250/1251 phosphorylation determines the rapid translocation of IGF1R from the plasma membrane to the Golgi apparatus, localization associated with the enhanced motility of tumor cells." (PMID 38892104, 2024). "Additionally, mice deficient in IGF-1R exhibited reduced tumor growth, cell proliferation, inflammation, and vascularization, and showed enhanced apoptosis after heterotopic tumor transplantation." (PMID 39638246, 2024). "Importantly, IGF1R has been shown to be implicated in the regulation of glycolysis in a variety of tumor." (PMID 37173768, 2023). "Moreover, a high IGF1R expression level was positively associated with tumour stage and a poor prognosis for overall survival in 79 patients with OSCC." (PMID 36978187, 2023). "MEK/MAPK pathway was analyzed in ES cells with disruption of MEK/MAPK or PI3K pathways via insulin growth factor-1 receptor (IGF-1R) neutralizing antibodies being associated with functional consequences including delayed time to primary tumor development and attenuated growth." (PMID 37888109, 2023). "Additionally, nuclear localization of the insulin-like growth factor-1 receptor (nIGF-1R) in tumor cells is emerging as a potentially vital factor in tumor pathophysiology and has been linked to adverse clinical outcomes in various cancers." (PMID 36831629, 2023).
tumor (continued). "The association between serum IGF-1 or tumor IGF-1R activity and PCa has been reported." (PMID 36831629, 2023). "IGF1R activation has been implicated in increasing tumor aggressiveness." (PMID 37549261, 2023). "High IGF-1R expression may play a role in tumour progression in CRC, as it is associated with both cell proliferation and differentiation, in agreement with our findings." (PMID 36890832, 2023). "Thus, reduced IGF1R was associated with altered E-cadherin and P-cadherin in tumor epithelial cells." (PMID 36568144, 2022). "Moreover, the level of IGF-1R protein is associated with tumor localization, grading, tumor growth, lymphatic vessel invasion, and mismatch repair protein expression status." (PMID 36295073, 2022). "In cancer, the dysregulation of IGFs/IGF-1R signaling can induce several hallmark genes of cancer and contribute to malignant transformation, tumor progression and resistance to a number of anti-tumor therapies such as radiation therapy and chemotherapy." (PMID 36233084, 2022). "Moreover, IGF1R deficiency in mice reduced tumor growth, proliferation, inflammation and vascularization, and increased apoptosis after tumor heterotopic transplantation." (PMID 35688943, 2022). "Therefore, these agents exhibit higher anti-tumor efficacy in multiple tumors and have a lower potential to cause hyperglycemia compared to IGF-1R TKIs." (PMID 36233084, 2022). "While silenced C-erbB-2 expression and inactivated IGF-1 signaling pathway caused decreased mRNA and protein expressions of IGF-1, IGF-1R and Akt, decreased cell proliferation, migration and invasion, prolonged G0/G1 phase and shortened S phase, increased cell apoptosis, and inhibited tumor growth." (PMID 34233689, 2021). "IGF/IGF-1R signaling mediates cell proliferation, cell survival, migration, and protein synthesis and can block apoptosis by expressing Myc and Akt1 in the liver, thereby causing invasion and metastasis of tumor cells." (PMID 33669204, 2021). "Thus, oncogenes and mutated tumor suppressors that target IGF-1R transcription appear to cause dysregulation of IGF-1R expression." (PMID 33669204, 2021). "Overexpression of IGF-1R has also been associated with a higher tumor grade, inhibition of apoptosis, increased proliferation rate, and angiogenesis in patients with pancreatic ductal adenocarcinoma, and with a lower survival in patients with colorectal cancer." (PMID 33322337, 2020). "Additionally, GH diminishes the anti-IGF1R tumor inhibition activity, suggesting that increased GH is a plausible cause of IGF1R inhibitor failure in the clinic." (PMID 33260481, 2020). "Indeed, IGF1R/PCNA colocalization in individual tumors was stronger in areas which are associated with higher proliferation (tumor invasive front) and genomic instability (dysplastic areas and cells with greater nuclear atypia)." (PMID 32701997, 2020). "Whether the association between coffee intake and recurrence-risk is modified by BMI and tumor-specific IGF1R expression in breast cancer patients has to our knowledge not been studied." (PMID 29928262, 2018). "We investigated whether the loss of IGF-1R function altered IL-6 expression in the tumor epithelial cell population by measuring IL-6 expression in the CD24+/CD29lo (luminal) and CD24+/CD29hi (basal) cell populations." (PMID 30458886, 2018). "The aim of this study was to evaluate if the prognostic impact of coffee consumption overall, and especially in tamoxifen-treated breast cancer patients, was partly mediated through associations with tumor-specific IGF1R protein expression and the patients’ BMI." (PMID 29928262, 2018). "In line with previously demonstrated biological mechanisms by coffee constituents in suppressing IGF1R levels in breast cancer cells in vitro, the present study further revealed that increasing coffee consumption was associated with lower tumor-specific IGF1R levels also in primary breast cancer." (PMID 29928262, 2018).